GNG7 (G protein subunit gamma 7)
Diseases named in the same sentence as GNG7 in open-access papers (continued):
Sharing a sentence is not in itself a finding about the gene and the disease.
cancer (29 papers, 2008 to 2025). A tumor composed of atypical neoplastic, often pleomorphic cells that invade other tissues. "Higher GNG7 expression correlates with better survival in some cancers, while lower expression is linked to poorer outcomes, particularly in LUAD." (PMID 40496619, 2025). "Our results show that GNG7 is downregulated in various cancers, including LUAD, and its expression is associated with patient prognosis." (PMID 40496619, 2025). "G protein γ subunit 7 (GNG7) has been implicated in the regulation of cell proliferation, apoptosis, and migration across various cancers." (PMID 40496619, 2025). "When contrasting stages I-II and stages III-IV cancer stages, a notable discrepancy in GNG7 expression was noted, with reduced expression linked to advanced cancer stages (P<0.01)." (PMID 40496619, 2025). "GNG7 encodes G Protein Subunit Gamma 7, involved in central nervous system function and cancer risk." (PMID 31092297, 2019). "Loss of chromosome 19p13.3, which includes the GNG7 locus, has been observed frequently in several cancers." (PMID 18219292, 2008). "GNG7 suppression was associated with greater invasiveness of cancer cells in the oesophageal wall and poorer prognosis." (PMID 18219292, 2008). "We employed the TCGA database to analyze the expression levels of GNG7 across various cancer types as well as normal tissue samples." (PMID 40496619, 2025). "In our study, we took an integrative approach to elucidate the relationship between GNG7 expression, immune system interactions, and cancer biological functions." (PMID 40496619, 2025). "The major enriched pathways included Arachidonic acid metabolism, Steroid hormone biosynthesis, Pathway in cancer, etc, and the major functional genes included the alox15b, gng7, hif1a, ppara, and pla2g." (PMID 41462646, 2025). "Consistent with this, data from the Oncomine and GEPIA tools also revealed that GNG7 was downregulated in diverse human cancers, including GC." (PMID 36863706, 2023). "The study revealed that GNG7 was downregulated in GC and inhibited cancer cell growth by blocking cell cycle progression and inducing apoptosis." (PMID 36863706, 2023). "In this study, we analyzed the expression of GNG7 in various cancers through Oncomine, UALCAN, and TIMER databases." (PMID 35281820, 2022). "In order to investigate the prognostic value of GNG7 expression in different types of cancers, we further analyzed the relationship between GNG7 expression and prognosis of cancer patients via PrognoScan database." (PMID 35281820, 2022). "Our survival analysis results in the database showed that GNG7 expression is correlated to the prognosis of different cancers, including CRC." (PMID 35281820, 2022). "To elucidate the expression pattern of GNG7 in cancers, we first evaluated the expression of GNG7 in 33 types of cancers by a systematic analysis based on the TCGA databases." (PMID 36159963, 2022). "GNG7 is G protein γ subunit 7, and its low expression is considered to be a key event in the occurrence of malignant tumors." (PMID 33727922, 2021). "GNG7 is a subunit of heterotrimeric G protein, which is commonly expressed in various tissues, but low in cancer." (PMID 33123291, 2020). "Our results showed that the GNG7 transcriptions in the five cancer cells were lower than in 293T, especially in U2OS and HeLa cancer cell lines." (PMID 27056891, 2016). "This and the previously published data indicate that GNG7 is likely to be generally down regulated in cancers." (PMID 27056891, 2016). "GNG7 (G protein γ subunit 7), a subunit of heterotrimeric G protein, is ubiquitously expressed in multiple tissues but is down-regulated in various cancers." (PMID 27056891, 2016). "Following validation by QMSP, one gene, guanine nucleotide-binding protein γ-7 (GNG7), was confirmed to be highly methylated in tumors and unmethylated in normal mucosal and salivary rinse samples demonstrating cancer-specific methylation in HNSCC tissues." (PMID 23403885, 2013).
cancer (continued). "To evaluate DNA methylation patterns in the promoter region of the GNG7 gene, we carried out bisulphite sequencing in five paired cancer and normal tissue specimens." (PMID 18219292, 2008). "It is worth describing that the GNG7 expression in cancer cell lines was low in comparison with samples from cancer tissues." (PMID 18219292, 2008). "For example, GNG7 is downregulated in a variety of malignancies, and overexpression of GNG7 can inhibit cell proliferation and increase cell death, indicating that GNG7 may be a protective factor in cancer." (PMID 39104385, 2024). "On the other hand, GNG7 is a promising therapeutic target for cancer." (PMID 37704946, 2023). "The expression of GNG7 in pan-cancer was obtained from TIMER." (PMID 37704946, 2023). "Considering these findings, it could be concluded that GNG7 suppresses GC cell growth by arresting the cell cycle at the S phase and promoting cancer cell apoptosis." (PMID 36863706, 2023). "Hence, these findings indicated that GNG7 can be regarded as a potential indicator for predicting the prognosis of certain types of cancer including CRC." (PMID 35281820, 2022). "GNG7 is ubiquitously expressed in multiple tissues but is down-regulated in various cancers." (PMID 35281820, 2022). "Meanwhile, it is worth noting that analysis of the Oncomine and TIMER databases revealed that the expression levels of GNG7 in various cancers were different relative to normal tissues, however, GNG7 was down-regulated in some cancers and up-regulated in others." (PMID 35281820, 2022). "GNG7 and ADCY1 may be an oncogene that regulated tumorigenesis and development through pathways in cancer and could be used as a biomarker of the diagnostic and prognostic value of PAAD." (PMID 34650124, 2021). "It has been demonstrated low expressed GNG7 in various cancers." (PMID 34635014, 2021). "The expression of GNG7 may be regulated by miR‐328 and demethylation drug 5‐AZAC restored GNG7 expression in other cancer cell lines, but the molecular mechanism of such effects in ccRCC remain unclear and warrant further investigation." (PMID 30945310, 2019). "Then, we supposed that the upregulated miR-552 might suppress the expression of GNG7 to promote the development of cancers of the digestive tract; however, this hypothesis needs to be confirmed with in vitro and in vivo experiments in future." (PMID 31737678, 2019). "However, the role of GNG7 in cancer is poorly understood and the significance of GNG7 gene expression in ccRCC remains unknown." (PMID 30945310, 2019). "Therefore, we speculated that clinical samples with stromal cells showed much higher GNG7 expression than the cancer cell lines." (PMID 18219292, 2008). "The correlation heat maps of GNG7 expression with immunoinhibitors, immunostimulators and major histocompatibility complex (MHC) molecules in different cancers were displayed respectively in." (PMID 35281820, 2022). "These genes are related to the immune system and tumors: GNG7 is related to PI3K-Akt and Chemokine, FKBP4 is related to Estrogen, and IGF2BP1 is related to miRNA in the cancer pathway, and CD40LG is related to the NF-kappa B and T cell receptors." (PMID 36249053, 2022). "The KEGG analysis on 13 selected genes showed that GNG7 and ADCY1 enriched in the Pathway in Cancer." (PMID 34650124, 2021). "To investigate the effect of GNG7 on ccRCC cell proliferation and viability, we used a CCLE database, which demonstrated that the GNG7 mRNA expression level was low in many cancer types." (PMID 30945310, 2019). "We observed that two genes (GNG7, ADCY1) meaningfully enriched in the Pathways in Cancer." (PMID 34650124, 2021). "In the present study, we find that GNG7 is down regulated in HeLa and U2OS cancer cell lines." (PMID 27056891, 2016).
cancer (continued). "Our results showed that after transfection with 0, 0.05, 0.1, 0.25, 0.5, or 1.0 μg/ml GNG7-FLAG plasmids, but not the FLAG vector control, for 48 hours, the apoptotic and dead cells increased in a dose-dependent manner, which indicates that GNG7 induces cell death to inhibit cancer." (PMID 27056891, 2016).
gastrointestinal tract cancer (2 papers, 2021 to 2022). "In gastrointestinal tract cancer, GNG7 suppresses cell growth in vitro and in vivo through upregulating the expression a cyclin-dependent kinase inhibitor p27Kip1." (PMID 34221006, 2021).
infection (2 papers, 2019 to 2024). The state of being infected such as from the introduction of a foreign agent such as serum, vaccine, antigenic substance or organism. "GNG7 and METTL17 have been identified as potential host factors for the infection of cyprinid herpesvirus 2 (CyHV-2) and HIV-1." (PMID 38542067, 2024).
nervous system diseases (2 papers, 2016 to 2021). "The mRNAs of Rgs9, Gpr88, Drd2, Sh3rf2, Tac1, Serpina 9, Rxrg, Drd1, Rasgrp2, Six3, Gpr6, Pdyn, Gng7, and Pde1b were all upregulated (p < 0.05); all of these have been reported to be more or less related to nervous system diseases." (PMID 33819195, 2021).
adenocarcinoma (1 paper, 2025). A common cancer characterized by the presence of malignant glandular cells. "With the application of immune checkpoint inhibitors in the treatment of adenocarcinoma, exploring the interaction between GNG7 and these treatment strategies has become particularly important." (PMID 40496619, 2025).
psychiatric disorder (1 paper, 2019). A disorder characterized by behavioral and/or psychological abnormalities, often accompanied by physical symptoms. "GNG7 also has trans-diagnostic evidence for involvement in other psychiatric disorders." (PMID 30755720, 2019).
GNG7 also shares sentences with these, for which no sentence is quoted: head and neck cancer (4 papers); head and neck squamous cell carcinoma (3); squamous cell carcinoma (3); Anxiety (2); cervical cancer (2); head and neck tumor (2); intrahepatic cholangiocarcinoma (2); schizophrenia (2); anxiety disorder (1); autism (1); autoimmune thyroid disease (1); bladder cancer (1); Bladder Urothelial Carcinoma (1); brain neuroblastoma (1); cardiovascular diseases (1); cholangiocarcinoma (1); Chronic colitis (1); cognitive decline (1); cognitive deficits (1); COVID-19 (1); dementia (1); diabetes (1); dysplasia (1); glioblastoma (1); Herpes simplex infection (1); Hypercholesterolemia (1); hypothyroidism (1); leukemia (1); lymph node metastasis (1); mastitis (1).
A further 9 diseases each share a sentence with GNG7 in 1 paper.